ENSG00000259200 (novel transcript)
Synonyms: LOC105370802
Gene: Long non-coding RNA gene on chromosome 15 (45,705,052 to 45,931,069, forward strand). Ensembl gene ENSG00000259200.
Diseases named in the same sentence as ENSG00000259200 in open-access papers:
ENSG00000259200 is named in the same sentence as 2 diseases in open-access papers, as found by Europe PMC text mining. Sharing a sentence is not in itself a finding about the gene and the disease.
ENSG00000259200 shares sentences with these, for which no sentence is quoted: cancer (1 paper); lung adenocarcinoma (1).